CDKN2A (cyclin dependent kinase inhibitor 2A)
Diseases named in the same sentence as CDKN2A in open-access papers (continued):
Sharing a sentence is not in itself a finding about the gene and the disease.
tongue cancer (3 papers, 2014 to 2024). A malignant neoplasm affecting the tongue.
ulcerative colitis (3 papers, 2004 to 2021). An inflammatory bowel disease involving the mucosal surface of the large intestine and rectum. "CDKN2A hypermethylation is among the major events associated with carcinogenesis and is also observed in non-neoplastic colonic mucosa in patients with ulcerative colitis (UC)." (PMID 33046033, 2020).
uterine cancer (3 papers, 2017 to 2025). Primary or metastatic malignant neoplasm involving the uterine corpus and/or the cervix. "The significant downregulation of CDKN2A in uterine cancer due to CTRP6 mutations may contribute to uncontrolled cell division, promoting tumor growth." (PMID 39979869, 2025). "Same information for predictive models of (b) IDH1-d, (c) SMARCA4-d, (d) CDKN2A-d, (e) HERC2-d, and (f) PTEN-d in central nervous system (CNS) cancers and (g) uterine cancers." (PMID 36883553, 2023).
alcohol- (2 papers, 2021 to 2025). "A further analysis of four patients with alcohol-related HCC, identified LOH in CDKN2A and CMM loci (involved in overexpression of HGF) in three patients." (PMID 33572904, 2021).
alcoholic liver diseases (2 papers, 2014 to 2025). A disorder caused by damage to the liver parenchyma due to alcohol consumption. "Additionally, the expression of CDKN1A and CDKN2A, as well as the presence of TAF, has been observed in non-alcoholic fatty liver disease, and TAF has also been reported in alcoholic liver disease." (PMID 39963130, 2025).
anemia (2 papers, 2018 to 2025). A reduction in the number of red blood cells, the amount of hemoglobin, and/or the volume of packed red blood cells. "The hemoglobin level at diagnosis was slightly greater in the CDKN2A/B deletion group than in the non-deletion group, indicating that the degree of anemia in these patients was milder than that in the non-deletion group." (PMID 40017529, 2025).
arteriosclerosis (2 papers, 2017 to 2020). A vascular disorder characterized by thickening and hardening of the walls of the arteries. "Another limitation is the lack of data on vascular CDKN2A/p16INK4a and p16INK4a expression in age- and gender-matched non-uremic patients with arteriosclerosis." (PMID 28192277, 2017).
benign hemangiomas (2 papers, 2013 to 2021). "Indeed, another report showed that deletion of Cdkn2a/ARF led to hemangioma formation in only 6.1% of all tumors analyzed, suggesting that co-deletion of ARF changes the spectrum of tumors caused by Cdkn2a deletion in addition to an increase in lethality." (PMID 33078209, 2021).
bladder (2 papers, 2010 to 2012). "Next, we assessed the frequency of CDKN2A methylation in tumor and non-tumor tissue samples of 34 patients with liver metastases and 11 patients with adenocarcinomas of the biliary tract and gall bladder (CCC-group) as well as from 7 patients with benign liver tumors." (PMID 20569442, 2010).
chronic gastritis (2 papers, 2016 to 2022). Inflammation of the stomach that is chronic in nature. "In addition, chronic gastritis, intestinal metaplasia, gastric adenoma, and gastric cancer show an increasing frequency of p16/cyclin-dependent kinase inhibitor 2A (CDKN2A) methylation." (PMID 27464701, 2016).
chronic hepatitis B (2 papers, 2024 to 2025). "High-throughput sequencing has also revealed copy number variations (amplification of MYC and deletions in CDKN2A) and mutational signatures linked to aflatoxin exposure and chronic hepatitis B infection." (PMID 40869967, 2025).
chronic hepatitis C (2 papers, 2010 to 2013). "In chronic hepatitis C patients, methylation frequencies in many TSGs, such as RASSF1, CDKN2A, APC, and RUNX3, were associated with shorter time-to-HCC occurrence." (PMID 24330717, 2013).
colitis (2 papers, 2020 to 2023). Inflammation of the colon. "Furthermore, in our results, the significant association of MIF polymorphisms with CIHM of CDKN2A were found in chronic continuous of clinical type and total colitis phenotype." (PMID 33046033, 2020). "In human colitis-associated tumors, inactivation of CDKN2A appears to be caused by DNA methylation rather than genetic mutations." (PMID 37845228, 2023).
collecting duct carcinoma (2 papers, 2016 to 2020). "In the rare RCC category, collecting duct carcinoma (CDC) harbors mutations in NF2, SETD2, SMARCB1, FH, and CDKN2A genes while renal medullary carcinoma is distinctively characterized by loss of SMARCB1/INI1 tumor suppressor protein." (PMID 32575429, 2020).
cutaneous T cell lymphoma (2 papers, 2020 to 2025). "Previous studies have suggested that METTL3, a key m6A methyltransferase, inhibits the proliferation and migration of cutaneous T-cell lymphoma (CTCL) cells by regulating the expression of CDKN2A." (PMID 40332203, 2025).
desmoplastic melanoma (2 papers, 2020 to 2023). A melanoma of the skin characterized by a proliferation of atypical spindled melanocytes in the dermis, in a background of abundant collagen. "For instance, CDKN2A mutations are present in 20% (4 out of 20 cases; 3 truncating mutations and one missense mutation) of desmoplastic melanoma, and these alterations predominantly affected either p16INK4a alone or p16INK4a along with p14ARF." (PMID 33076392, 2020).
duodenal adenocarcinoma (2 papers, 2022 to 2025). A carcinoma that arises from glandular epithelial cells of the duodenum. "However, when comparing duodenal adenocarcinomas to cancers of other small bowel sites, both CDKN2A (18% vs. 10%) and ERBB2 (13% vs. 4%) alteration rates were higher in duodenal adenocarcinomas." (PMID 35267592, 2022).
E. coli infection (2 papers, 2022). "Escherichia coli infection regulates the transcription patterns of DNMT-1, and inducing CpG hypermethylation reduces the expression of the cell-cycle inhibitor CDKN2A in human uroepithelial cells." (PMID 35323594, 2022).
endocervical adenocarcinoma (2 papers, 2009 to 2021). An adenocarcinoma that arises from the endocervix.
ependymal tumor (2 papers, 2007 to 2023). A group of neoplasms which arise from the ependymal lining of the cerebral ventricles and from the remnants of the central canal of the spinal cord. "MLPA was performed for CDKN2A HD in 20 ependymal tumors, including EPN-ZFTA." (PMID 37322295, 2023). "The relationship between the CDKN2A hemizygous deletion and the expression of MTAP or p16 has not yet been reported for ependymal tumors." (PMID 37322295, 2023).
epilepsy (2 papers, 2023 to 2025). A brain disorder characterized by episodes of abnormally increased neuronal discharge resulting in transient episodes of sensory or motor neurological dysfunction, or psychic dysfunction.
gastrinoma (2 papers, 2016 to 2023). "Of note, CDKN2A hypermethylation seems to be a hallmark of gastrinomas, since it occurs in 52-62% of gastrinomas but only in 17% of insulinomas." (PMID 27418145, 2016). "However, the methylation of tumor suppressor CDKN2A gene is the most common epigenetic alteration observed in gastrinoma." (PMID 36830839, 2023).
glioneuronal tumor (2 papers, 2020 to 2023). "In summary, our findings highlight a novel type of glioneuronal tumor driven by different RTK fusions accompanied by recurrent alterations in ATRX and homozygous deletions of CDKN2A/B." (PMID 36933012, 2023).
Hepatosplenomegaly (2 papers, 2022 to 2023). Simultaneous enlargement of the liver and spleen. "Children with ALL in the CDKN2A rs3088440 were more likely to have hepatosplenomegaly (P = 0.019) and high risk (P = 0.014) than the wild group." (PMID 37314514, 2023). "The children with CDKN2A rs3088440 mutations were more likely to develop hepatosplenomegaly and be at higher risk than the wild group." (PMID 37314514, 2023). "Children with CDKN2A rs3088440 mutation were more likely to develop hepatosplenomegaly and high risk than the wild group." (PMID 37314514, 2023).
infarction (2 papers, 2025). A localised pathological necrosis of tissue resulting from obstruction of the blood supply usually by a thrombus, an embolus, or vascular torsion. "The expression of Cdkn2a was significantly increased in the WT mice infarction area in comparison to their intact myocardium (p = 0.011), while in the Chr4Δ70kb/Δ70kb mice, the expression remained at a low level." (PMID 40405527, 2025). "However, in the infarction scar area, consisting mostly of fibrous tissue, the expression of Cdkn2a was increased in WT mice, yet both Cdkn2a and ‐b remained significantly lower in Chr4Δ70kb/Δ70kb mice, suggesting that Ak148321 may regulate the Cdkn2a/b expression." (PMID 40405527, 2025).
interstitial lung disease (2 papers, 2021 to 2024). A diverse group of lung diseases that affect the lung parenchyma. "To confirm that cellular senescence is found in fibrotic interstitial lung disease in humans, we performed RNA in situ hybridization (ISH) with a probe specifically designed for the p16ink4a transcript variant of the Cdkn2a gene locus in diseased lung." (PMID 38976646, 2024). "All interstitial lung disease patient tissue sections showed mild expression of Cdkn2a in the aberrant and airway epithelial cells lining the honeycomb cysts, but notably, not in fibroblasts in the fibroblastic foci, which define the site of active matrix deposition." (PMID 38976646, 2024).
intimal sarcoma (2 papers, 2024 to 2025). A malignant neoplasm arising from the large blood vessels. "Recent evidence from studies of milademetan in intimal sarcoma suggests that cyclin-dependent kinase inhibitor 2A (CDKN2A) loss and amplified twist-related protein 1 (TWIST1) may serve as additional biomarkers associated with enhanced anti-tumor activity in MDM2-amplified tumors." (PMID 41170373, 2025).
kidney tumors (2 papers, 2017 to 2021). "A previous study in genetically engineered mouse models had found that MYC activation with CDKN2A deletion and VHL deletion together produce kidney tumors that closely resemble human clear cell RCC41." (PMID 33547292, 2021). "MYC activation results in highly penetrant pRCC tumours (MYC), while MYC activation, when combined with Vhl and Cdkn2a (Ink4a/Arf) deletion (VIM), produce kidney tumours that approximate human ccRCC." (PMID 28593993, 2017).
metastasis (2 papers, 2024 to 2025). The spread or migration of cancer cells from one part of the body (where they first appeared) to another. "A meta-analysis of CRC revealed a significant association between CDKN2A hypermethylation and lymphovascular invasion, lymph node metastasis, and proximal tumor location." (PMID 40426913, 2025).
microphthalmia (2 papers, 2013 to 2024). Congenital or developmental anomaly in which the eyeballs are abnormally small. "Overexpression of Cdkn2b in Xenopus microphthalmia models correlated with reduced cell proliferation due to cell cycle misregulation, and upregulation of CDKN2A and CDKN2B reduces proliferation in the developing retina." (PMID 38821055, 2024). "Interestingly, reduced expression of Cdkn2a in TASP1-deficient mice significantly decreased cranial and ocular malformations, including microphthalmia, suggesting inhibition of these genes may be required for correct retinal progenitor proliferation to drive ocular morphogenesis." (PMID 38821055, 2024).
mucoepidermoid carcinoma (2 papers, 2015 to 2023). A carcinoma morphologically characterized the presence of cuboidal mucous cells, goblet-like mucous cells, squamoid cells, cystic changes, and a fibrotic stromal formation. "They reported that expression of cyclin D1, CDK4 and CDKN2A were significantly higher in malignant salivary gland tumors (including adenoid cystic carcinoma and mucoepidermoid carcinoma) when compared to normal salivary gland." (PMID 26247885, 2015). "CDKN2A and CDKN2B GA were common in mucoepidermoid carcinoma (MECa) (52.5 and 30.5%)." (PMID 36831055, 2023).
odontogenic neoplasm (2 papers, 2020 to 2025). A benign or malignant neoplasm arising from tooth-forming tissues. "At present, it is uncertain which of the proteins encoded by the CDKN2A locus needs to be lost to cooperate with IKKβ overexpression in odontogenic tumour formation." (PMID 31900382, 2020).
optic nerve glioma (2 papers, 2005 to 2024). A glioma that affects the optic nerve. "Moreover, NGS studies show that chromosomal alterations by NF1 and CDKN2A pathogenic gene variants contribute largely to the development of optic nerve glioma." (PMID 38540335, 2024). "NGS studies indicate that a child predisposed to optic nerve glioma due to NF1 and CDKN2A genetic variants inherits these conditions from their parents." (PMID 38540335, 2024).
periampullary adenocarcinoma (2 papers, 2019 to 2024). An adenocarcinoma that arises from the periampullary region. "Herein, we describe that the pattern of the mutational status, such as CDKN2A and APC mutations, of periampullary adenocarcinomas differs by morphologic subtype." (PMID 32914025, 2019). "In a study with pancreatic and periampullary cancers, in which CDKN2A HD is common (40%), it was reported that CDKN2A HD was seen in half of the cases without MTAP HD." (PMID 38109891, 2024).
periodontal disease (2 papers, 2023 to 2025). "Furthermore, CXCL5, ADM, FGF9, AIMP1, STC1, and CDKN2A might have a significant impact on the development of HNSC caused by periodontal disease." (PMID 37675228, 2023).
polyp (2 papers, 2007 to 2014). A usually exophytic mass attached to the underlying tissue by a broad base or a thin stalk. "Others have demonstrated a direct correlation between aberrant methylation of APC, DKKI, CDKN2A/p16, and SFRP4 in the apparently normal colon mucosa of cancer patients and, to a lesser extent, of polyp patients." (PMID 24760232, 2014).
prediabetes (2 papers, 2015 to 2022). "The present data showed an increased prediabetes risk with an additive effect of the alleles of CDKN2A-rs10811661 (OR per T allele = 1.22, 95 % CI = 1.04–1.44, P = 0.017)." (PMID 26334876, 2015). "There were many factors influencing the association between the CDKN2A-rs10811661 polymorphism and prediabetes, including bias selection of subjects, confounding factors such as socio–economic condition, and lifestyle factors." (PMID 26334876, 2015). "Because of the small contribution of the single CDKN2A–rs10811661 polymorphism, it is necessary to conduct a large-scale prospective study on prediabetes and T2D in Vietnamese population." (PMID 26334876, 2015). "Our finding supports the association of the CDKN2A-rs10811661 polymorphism with prediabetes reported in previous case–control studies in Asian populations." (PMID 26334876, 2015). "Given the multifactorial pattern of prediabetes, the contribution of the CDKN2A-rs10811661 polymorphism varies among populations depending on the socio–economic status, lifestyle factors, genetic background, and risk − factor profile of each population." (PMID 26334876, 2015). "This cross-sectional study aimed to investigate the independent risk factors for prediabetes, considering the contribution of genetic factors (TCF7L2-rs7903146, IRS1-rs1801278, INSR-rs3745551, CDKN2A-rs10811661, and FTO-rs9939609), socio-economic status, and lifestyle factors." (PMID 26334876, 2015). "Thereby, the statistically significant association between the CDKN2A-rs10811661 polymorphism and prediabetes was found to be independent of the traditional risk factors." (PMID 26334876, 2015). "Therefore, the study was designed to investigate both genetic (TCF7L2-rs7903146, IRS1-rs1801278, INSR-rs3745551, CDKN2A-rs10811661, and FTO-rs9939609) and environmental factors for prediabetes in a Vietnamese population." (PMID 26334876, 2015).
prostate adenocarcinoma (2 papers, 2022 to 2024). "However, there was a weak negative correlation for TNRC6C in TGCT; TFDP1 in LAML; CDKN2C in prostate adenocarcinoma (PRAD); and CDKN2A in KIRC and THCA." (PMID 35911954, 2022).
rectal NETs (2 papers, 2023 to 2024).
salivary carcinomas (2 papers, 2010 to 2024). "CDKN2A/B CDKN2B loss has been associated with high-grade salivary gland carcinomas and was also positive in our case." (PMID 39329865, 2024).
salivary gland cancer (2 papers, 2015 to 2024). A primary or metastatic malignant neoplasm that affects the major or minor salivary glands. "Although it is unclear why CDKN2A protein expression was higher in malignant salivary gland tumors in this study, it is possible that the cyclin pathway is involved in tumorigenesis of salivary gland cancers." (PMID 26247885, 2015).
salivary gland tumors (2 papers, 2015 to 2023). "The second most common aberrations involved the cyclin pathway (CCND1, CDK4/6 or CDKN2A/B), which was abnormal in 26.5% of patients (31/117) with salivary gland tumors." (PMID 26247885, 2015).
schwannomatosis (2 papers, 2018 to 2022). The least frequent form of the rare genetic disorder neurofibromatosis. "In contrast to DGCR8, evidence supporting the involvement of variants in CDKN2A and COQ6 in schwannomatosis pathogenesis is less conclusive." (PMID 35723634, 2022). "Screening of the coding region of DGCR8, COQ6, CDKN2A, and CDKN2B was carried out, based on previous reports that point to these genes as potential candidate genes for schwannomatosis." (PMID 35723634, 2022).
seminoma (2 papers, 2010 to 2021). A radiosensitive malignant germ cell tumor found in the testis (especially undescended), and extragonadal sites (anterior mediastinum and pineal gland). "In the subsequent studies, the same researcher group showed that LOH of the CDKN2A was found in two (6%) non-seminomas cases with a yolk sac tumor component, and LOH of the RB1 was also found in two (6%) non-seminomas with an embryonal carcinoma component." (PMID 34068019, 2021).